ENSG00000260007 (novel protein)
Gene: Protein-coding gene on chromosome 15 (68,184,032 to 68,229,718, reverse strand). Ensembl gene ENSG00000260007.
Genetic constraint (gnomAD): Loss-of-function variants: 12 observed, 10.2 expected, observed/expected ratio (o/e) 1.18, 90% interval 0.75 to 1.79. Missense variants: 125 observed, 107.21 expected, observed/expected ratio (o/e) 1.17, 90% interval 1.01 to 1.35. Synonymous variants: 55 observed, 42.97 expected, observed/expected ratio (o/e) 1.28, 90% interval 1.03 to 1.6.